ZFAT (zinc finger and AT-hook domain containing)
Description:
May be involved in transcriptional regulation. Overexpression causes down-regulation of a number of genes involved in the immune response. Some genes are also up-regulated (By similarity).
Synonyms: KIAA1485; ZFAT1; ZNF406; AITD3
Tractability: PROTAC: ubiquitination databases record sites on it.
Gene: Protein-coding gene on chromosome 8 (134,477,788 to 134,713,127, reverse strand). Ensembl gene ENSG00000066827.
Subcellular location: Nucleus; Cytoplasm, cytosol
Subcellular location (Human Protein Atlas): Nuclear bodies; Nucleoplasm
Gene Ontology:
Molecular function: protein binding; DNA-binding transcription factor activity, RNA polymerase II-specific; RNA polymerase II cis-regulatory region sequence-specific DNA binding; DNA-binding transcription activator activity, RNA polymerase II-specific
Biological process: regulation of DNA-templated transcription; positive regulation of transcription by RNA polymerase II; regulation of transcription by RNA polymerase II
Cellular component: nucleus; cytosol
Genetic constraint (gnomAD): Loss-of-function variants: 61 observed, 111.13 expected, observed/expected ratio (o/e) 0.55, 90% interval 0.45 to 0.68. The upper end of that interval is the gene's LOEUF score, 0.68, which puts it in group 2 of 6, group 1 being the genes least tolerant of losing a copy. Missense variants: 1,429 observed, 1,604.2 expected, observed/expected ratio (o/e) 0.89, 90% interval 0.85 to 0.93. Synonymous variants: 679 observed, 626.01 expected, observed/expected ratio (o/e) 1.08, 90% interval 1.02 to 1.16.
Homologues: Orthologues: chimpanzee ZFAT (99% identical), macaque ZFAT (98% identical), guinea pig ZFAT (90% identical), rat Zfat (88% identical), mouse Zfat (88% identical), dog ZFAT (87% identical), pig ZFAT (87% identical), rabbit ZFAT (79% identical), tropical clawed frog zfat (63% identical), zebrafish zfat (57% identical), Drosophila melanogaster CG10543 (18% identical), Caenorhabditis elegans spr-4 (17% identical). Paralogues in human: PRDM15 (16% identical), ZFX (14% identical), ZFY (14% identical), ZNF711 (12% identical), ZBTB11 (12% identical), E4F1 (12% identical), ZNF792 (11% identical), ZNF551 (11% identical), ZNF304 (11% identical), ZNF587B (11% identical), ZNF256 (11% identical), ZNF549 (10% identical), and 26 more.
Diseases named in the same sentence as ZFAT in open-access papers:
ZFAT is named in the same sentence as 10 diseases in open-access papers, as found by Europe PMC text mining. Sharing a sentence is not in itself a finding about the gene and the disease. The quoted sentences say what the papers report.
autoimmune thyroid disease (6 papers, 2013 to 2022). Inflammatory disease of the thyroid gland due to autoimmune responses leading to lymphocytic infiltration of the gland. "ZFAT is a protein-coding gene associated with vulnerability for autoimmune thyroid disease, and overexpression is linked to down-regulation of genes involved in the immune response." (PMID 35395780, 2022). "The human ZFAT gene was originally identified as a susceptibility gene for autoimmune thyroid disease." (PMID 24098453, 2013). "ZFAT was originally identified as a candidate susceptibility gene for autoimmune thyroid disease." (PMID 24098453, 2013). "Zinc finger and AT-hook domain containing (ZFAT) is a zinc finger protein; it is a transcriptional regulator involved in apoptosis and cell survival, and it resides in a susceptibility locus for autoimmune thyroid disease." (PMID 33333988, 2020). "It resides in the ZFAT gene, which is related to autoimmune thyroid disease." (PMID 30153862, 2018). "ZFAT is a transcriptional regulator, containing eighteen C2H2-type zinc-fingers and one AT-hook, involved in autoimmune thyroid disease, apoptosis, and immune-related cell survival." (PMID 25801860, 2015).
breast carcinoma (1 paper, 2016). "Among the genes down-regulated in this GO term were transcriptional repressors of immune system such as ZFAT (Zinc Finger Protein 406, FC = 2.4); BRCA2 (Breast Cancer 2, Early Onset, FC = 3.2), and ZNF160 (Zinc Finger Protein 160, FC = 2.5)." (PMID 27427759, 2016).
cancer (4 papers, 2014 to 2025). A tumor composed of atypical neoplastic, often pleomorphic cells that invade other tissues. "Both GRB10 and ZFAT are known to play a role in regulating hematopoietic stem cell self-renewal and haematopoiesis and several studies revealed an association with cancer progression." (PMID 28912427, 2017). "A number of known and previously unknown oncogenes were identified, some of which have already been reported to be associated with cancer, including: ADCY8, ZFAT, BAI1, PTK2, FBXL6, FOXH1, HSF1, and UGT2A1." (PMID 25372838, 2014). "The relationship of Lnc-ZFAT-1 with cancer has not been reported in studies and needs to be further explored." (PMID 35252170, 2022).
tumor (3 papers, 2023 to 2025). "In contrast, patients with insufficient expression of SORBS2, PAM, ZFAT, DOCK7, ERMAP, BTF3, and GUSB in the tumor tissues had shorter survival duration than patients in the high-expression group." (PMID 37315301, 2023).
ZFAT also shares sentences with these, for which no sentence is quoted: glioma (1 paper); hematologic cancer (1); Miscarriage (1); preeclampsia (1); sarcopenia (1); uterine cancer (1).